ADAM9 (ADAM metallopeptidase domain 9)
Diseases named in the same sentence as ADAM9 in open-access papers (continued):
Sharing a sentence is not in itself a finding about the gene and the disease.
cardiac disease (2 papers, 2016 to 2024). "To further investigate cardiac disease in EMCV-infected WT and Adam9 KO mice, we performed immunohistochemistry analyzing troponin-T (to identify cardiomyocytes) and wheat germ agglutinin (WGA) (to delineate cell membranes and thereby cell damage)." (PMID 38755212, 2024). "To understand the mechanism(s) of cardiac disease and early mortality in EMCV-infected Adam9 KO mice, we tested the hypothesis that ADAM9 may be involved in the innate antiviral response." (PMID 38755212, 2024).
retinal disorder (2 papers, 2018 to 2020). Any disease or disorder of the retina. "This is an unusual and infrequently encountered pattern of degeneration, but one that is shared with other monogenic retinopathies, where the underlying gene regulates cell–cell adhesion (ADAM9, CDH3)." (PMID 29391521, 2018). "Therefore, ADAM9 can induce retinal disorders as well as pathological vascular diseases." (PMID 33096780, 2020). "Previous studies found that there was no major developmental defect except later retinal disorder in ADAM9 knockout mice." (PMID 33096780, 2020).
benign tumors (1 paper, 2020). "Therefore, our data might be a first hint that ADAM9 plays a similar role in VS and its expression might induce progression or possibly reduce cell death in these benign tumors." (PMID 33176868, 2020).
cardiovascular disease (1 paper, 2017). "We found that ANGPT2, PLAT (tPA), SERPINE1 (PAI-1), and VEGFA, which are involved in cardiovascular disease, were influenced in ADAM9 knockdown cells." (PMID 29118335, 2017).
endocrine neoplasms (1 paper, 2004). "In this study, we demonstrate that ADAM9 expression distinguishes PDACs from pancreatic acinar cell carcinomas and endocrine tumours." (PMID 14997207, 2004). "All endocrine tumours of the pancreas lacked cytoplasmic expression of ADAM9." (PMID 14997207, 2004). "Interestingly, endocrine neoplasms did not express ADAM9, although the islet cells in the normal pancreas displayed consistent granular cytoplasmic staining." (PMID 14997207, 2004).
respiratory disease (1 paper, 2024). "Some of the identified candidate genes, such as G Protein-Coupled Receptor Kinase 7 (GRK7), ADAM metallopeptidase domain 9 (ADAM9), furin, paired basic amino acid cleaving enzyme (FURIN), and Integrin Subunit Alpha V (ITGAV) were previously associated with bovine respiratory disease susceptibility." (PMID 38892353, 2024).
ADAM9 also shares sentences with these, for which no sentence is quoted: lymph node metastasis (3 papers); cervical squamous cell carcinoma (2); ductal adenocarcinoma (2); leukemia (2); oligodendroglial tumor (2); Retinal Diseases (2); amyloidosis (1); atherosclerosis (1); autism spectrum disorder (1); Autoimmunity (1); autosomal recessive cone-rod dystrophies (1); chronic pancreatitis (1); cone-rod dystrophy 3 (1); diabetic retinopathy (1); Fibroadenoma (1); head and neck tumor (1); Hearing impairment (1); heart failure (1); hemangiosarcomas (1); influenza (1); invasive carcinoma (1); Kidney (1); liver (1); liver fibrosis (1); lymphoma (1); male infertility (1); Neoplasm of the pancreas (1); neuroblastoma (1); non-Hodgkin lymphoma (1); oral disease (1).
A further 7 diseases each share a sentence with ADAM9 in 1 paper.